EPHA2 (EPH receptor A2)
Diseases named in the same sentence as EPHA2 in open-access papers (continued):
Sharing a sentence is not in itself a finding about the gene and the disease.
tumor (continued). "In vivo PET imaging in subcutaneous and orthotopic PDAC models confirmed high tumor uptake and minimal off-target binding, confirming EphA2 as a valid imaging target." (PMID 40225586, 2025). "EphA2 is overexpressed in many human cancers, where it promotes tumor growth, metastasis, and stem properties 7-9." (PMID 39897046, 2025). "Treatment with DS-8895a inhibited tumor growth of EphA2-positive human breast and gastric cancers in xenograft models." (PMID 40236294, 2025). "EPHA2 emerges as a critical regulator of tumor cell death, with roles that are context-dependent and tumor-specific." (PMID 40919148, 2025). "In particular, elevated EphA2 expression has been shown to correlate with increased tumor aggressiveness, poor prognosis, and reduced survival in patients with RCC." (PMID 41440001, 2025). "This study systematically reviews the molecular mechanisms by which NPs and TCM formulations inhibit VM formation across various tumor types, and summarizes multiple core intervention targets, including VE-cadherin, EphA2, MMPs, Twist1, HIF-1α, and PI3K/Akt." (PMID 41019994, 2025). "While this study provides evidence of the efficacy of EphA2 CAR-T/NK cells against EphA2-expressing tumor cells, certain limitations must be acknowledged." (PMID 40181964, 2025). "In the EphA2-knockdown group, tumor progression was reduced compared with that in the control group." (PMID 41440001, 2025). "Unlike that study, we directly silenced EphA2 using shRNA in a syngeneic, immunocompetent orthotopic model, providing in vivo mechanistic evidence that EphA2 depletion attenuates tumor growth and apoptosis resistance while suppressing the EphA2/FAK/RhoA axis." (PMID 41440001, 2025). "Lungs bearing EphA2-overexpressing tumors had significantly higher percentages of GFP+ KPL tumor cells compared to controls." (PMID 40867322, 2025). "The recommended Phase II dose (RP2D) of 6.5 mg/m2 every two weeks achieves optimal therapeutic exposure, demonstrating significant antitumour activity with measurable tumour regression in EphA2-positive malignancies." (PMID 40725089, 2025). "In the context of EphA2 ADCs, it is therefore critical to optimally deliver conjugated payloads while minimizing tumor metastasis and limiting non‐canonical signaling." (PMID 40411427, 2025). "Proteins downregulated in KO tumours with roles in regulating adhesion and angiogenesis included EphA2, integrin ITGB5, MCAM, and MYLK (myosin light chain kinase)." (PMID 41226720, 2025). "It is noteworthy that EphA2 has a dual function in cancers because it also has a tumor-promoting effect." (PMID 40943407, 2025). "This study provides in vivo evidence identifying EphA2 as a potential target to mediate the suppression of tumor progression in RCC." (PMID 41440001, 2025). "This not only highlights EphA2’s role in tumor immunology but also provides translational insight into the effects of current EphA2-targeting therapies on the tumor microenvironment." (PMID 40867322, 2025). "Our findings demonstrate potent dose-dependent cytotoxicity in PDAC cells and significant tumor growth inhibition in vivo, supporting EphA2-targeted alpha therapy as a novel and effective strategy." (PMID 40225586, 2025). "Nevertheless, this study demonstrates the potential for inhibition of EphA2 in RCC to suppress tumor progression." (PMID 41440001, 2025). "Collectively, these findings indicate that EphA2 not only promotes tumor aggressiveness but also contributes to adaptive resistance against tyrosine kinase inhibitors." (PMID 41440001, 2025). "We studied the association of rs4702 (FURIN) and rs6603883 (EPHA2) polymorphisms with the classical indicators of NPC prognosis: TNM stage, local tumor invasion (T), lymph node involvement (N), and the presence of metastasis (M)." (PMID 40943407, 2025).
tumor (continued). "Although EphA2 has previously been shown to facilitate lung tumor growth and metastasis through tumor cell-intrinsic mechanisms, this is one of the first studies that shows an immune-mediated phenotype." (PMID 40867322, 2025). "Tumor burden was reduced in the EphA2-knockdown group according to in vivo BLI on days 14 and 18 and an ex vivo test (p = 0.021, p = 0.043, p = 0.021)." (PMID 41440001, 2025). "EphA2 overexpression in the tumor significantly downregulated surface activation markers CD44, CD69, and CD25 on CD8+ T cells via flow cytometry." (PMID 40867322, 2025). "This dual-action design capitalises on EphA2’s tumour-selective expression, minimising off-target effects while maximising antineoplastic activity." (PMID 40725089, 2025). "EphrinA2 (EphA2), a member of the Eph family of receptor tyrosine kinases, is overexpressed in the tumor cells of several types of cancer." (PMID 41440001, 2025). "[68Ga]AJ201 demonstrates several key advantages over previously studied EphA2-targeting radiotracers, including higher tumor uptake and improved tumor selectivity." (PMID 40225586, 2025). "Leveraging genomic data sets and immunohistochemical (IHC) analyses of human tumor samples, we demonstrate the potential of EphA2 as a molecular radiotherapy target in PDAC." (PMID 40225586, 2025). "Reanalysis of existing single-cell datasets, we observed that the predominant expression of EPHA2 in stromal and epithelial cells corroborates previous findings regarding its role in the tumor microenvironment." (PMID 40919148, 2025). "EphA2 in the tumor cell can signal in an ephrin ligand-dependent or -independent manner, and it can even be packaged into extracellular vesicles to initiate signaling from a distance." (PMID 40867322, 2025). "The next-generation oHSV C134 has been genetically engineered to express a tumor-associated antigen (TAA), EphA2, to enhance TAA immune recognition and improve the anti-tumor activity of oHSV." (PMID 39895691, 2025). "Following the injection of EphA2 or control shRNA Renca–Luc cells into the mouse kidney to generate the orthotopic RCC tumor model, luciferase activity in the ROI was determined as the total flux using in vivo BLI." (PMID 41440001, 2025). "The proteomic identification of upregulated EphA2 and EPH-ephrin pathway components in PAK4KO cells provides a mechanistic link, as EphA2 promotes VM in aggressive cancers by enabling tumour cell plasticity and vessel-like structure formation." (PMID 41294859, 2025). "In summary, studies on Eph-Ephrin in AdCC, revealed heightened expression of EphA2 and ephrinA1, particularly in the solid pattern, correlating with tumor aggressiveness." (PMID 40421081, 2025). "VEGF, TGF-β, CXCR4, Cav-1, Wnt7a, EGFR and EPHA2 enhance vascular formation and influence tumor microenvironment dynamics." (PMID 40486870, 2025). "Although both studies demonstrate that tumor cell-specific EphA2 has a detrimental impact on T-cell-mediated immunity, one suggests that granulocytic myeloid cells play an intermediary role, while the other suggests monocytic myeloid cells." (PMID 40867322, 2025). "Our findings underscore the importance of NK cells in anti‐tumour immunity and highlight EphA2 as a critical oncotarget, with higher NK cell scores correlating with better survival in OS patients." (PMID 39763064, 2025). "EphA2-directed CAR T cells enhance anti-tumor responses by increasing IFN-γ and OX40 expression, and their efficacy improves further when combined with PD-1 blockade." (PMID 41200151, 2025). "EphA2 inhibition slowed the healing rate of wounded cultures and reduced the number, density, and size of tumor colonies." (PMID 41440001, 2025). "The results showed that compared with the control group, the tumor volume and mass were significantly increased in the EphA2 OE group, while the tumor mass and volume were significantly reduced in the EphA2 KD group." (PMID 39050762, 2024).
tumor (continued). "Studies on numerous cancer models have highlighted EphA2’s dual and often contradictory action, which can be attributed to EphA2′s interactions involving multiple pathways and different ligands, as well as the heterogeneity of the tumor microenvironment." (PMID 39596256, 2024). "In preclinical models of ovarian, breast, and pancreatic cancer, the inhibition of EphA2 decreased tumor growth and increased survival." (PMID 38279277, 2024). "Cancer vaccines are designed to stimulate patients’ immune systems and induce a response against EphA2-expressing tumor cells." (PMID 39596256, 2024). "In contrast to the cancer-promoting epidermal growth factor receptor (EGFR), EphA2 exerts tumor-suppressive effects through the ligand-dependent tyrosine phosphorylation (pY588) of specific tyrosine residues in the presence of its ligand." (PMID 39766211, 2024). "The nude mouse xenograft tumor models were used to observe the VM formation after knocking down or overexpressing EphA2." (PMID 39050762, 2024). "BT5528, a PDC that targets EphA2, can accumulate in tumor tissues at a minimal plasma concentration, increasing the selectivity to eradicate tumor cells while minimizing systemic toxicity." (PMID 38429828, 2024). "With regard to immunotherapy, a tumor antigen was evaluated in liver metastatic mice transfected with EphA2-positive CRC and showed antitumor effects." (PMID 38651144, 2024). "For instance, anti-EphA2 mAbs have developed as agonistic antibodies, effectively inhibiting tumor growth and angiogenesis by inducing receptor phosphorylation and subsequent anticancer effects." (PMID 38811954, 2024). "The results showed that PAAD tumor tissues have aberrantly high EphA2 expression levels compared to normal tissues." (PMID 39839790, 2024). "Although the role of other members of the Eph family has also been explored in tumours, EphA2 is extremely arresting." (PMID 38916835, 2024). "Treatment with EphA2-targeted CAR-T cells significantly extended the survival of tumor-bearing mice and effectively inhibited MB metastasis to the spinal cord." (PMID 39506843, 2024). "Recent studies have shown that EphA2 can additionally support tumorigenesis by promoting tumor immune evasion." (PMID 39596256, 2024). "In the transplanted MHCC97-H tumor tissues of nude mice, immunofluorescence experiments showed mild concordance between EphA2 and HIF-1a in terms of expression location and expression intensity (Pearson’s R value = 0.49)." (PMID 39050762, 2024). "Studies in animal models have demonstrated that EphA2 is critically important for tumor growth in HCC." (PMID 39839790, 2024). "EphA2 is normally expressed in rapidly proliferating cells and has previously been studied extensively for its roles in tumor metastasis and carcinogenesis." (PMID 39466050, 2024). "Complementing these findings, they identified by western blotting that Eph2 was more expressed in ESCC cell lines than in untransformed cell lines, suggesting that the level of the EphA2 protein reflects the tumor’s malignancy." (PMID 39839790, 2024). "EphA2-a-CAR-T cells showed higher tumor repression (with E:T ratios of 1:1 and 10:1, 76.05% and over 85%, respectively)." (PMID 38339374, 2024). "This review delves into the therapeutic challenges of BCA, emphasizing the roles of interleukin-13 receptor α2 (IL-13Rα2) and erythropoietin-producing hepatocellular receptor A2 (EphA2) in tumor progression and resistance." (PMID 38612592, 2024). "The SLAP–UBE4E interaction induces EphA2 ubiquitination and proteasomal degradation, therefore hindering EphA2 oncogenic signaling in tumor cells." (PMID 39596256, 2024). "Accordingly, inhibition of CAV1 in mice reduced vascular density and tumor growth as well as in vitro inhibition of EphA2." (PMID 39596256, 2024). "We targeted a proteolytic epitope on the cell surface receptor, EPH Receptor A2 (EphA2), that is known to transform it from a tumor suppressor to an oncoprotein." (PMID 38683990, 2024).
tumor (continued). "In conclusion, the exploration of IL-13Rα2 and EphA2 within the context of BCA has highlighted their pivotal roles in tumor progression, metastasis, and the development of resistance mechanisms." (PMID 38612592, 2024). "They demonstrated that the activation of EphA2 leads to increased tumor growth and resistance to apoptosis." (PMID 39063221, 2024). "EphA2 cleavage and processing by metalloproteases is a mechanism by which cancer cells can escape ligand-dependent tumor-suppressive signaling." (PMID 39596256, 2024). "For instance, EPHA2 expression on extracellular vesicles can influence nearby ephrin-A1-expressing tumor cells." (PMID 38612645, 2024). "The same was observed for EPHA2 kinase activity, found to be significantly increased both in epithelial cells and tumor‐intrinsic Phos2 subtypes." (PMID 38650175, 2024). "Molecular, genetic, biochemical, and pharmacological approaches have been developed to target EphA2 and its signaling pathway aiming to interfere with its tumor-promoting effects or as a carrier for drug delivery." (PMID 39252029, 2024). "CAR-T cells, regardless of having an additional co-stimulatory domain, proliferated in the presence of EphA2+ tumor cells, exhibited cytolytic activity and produced cytokines: IFN-γ and IL-2." (PMID 38339374, 2024). "EphA2 induces anti-tumor immunity by generating EphA2-specific CD8+ T cells that are effective against resistant tumors." (PMID 39906660, 2024). "In vitro studies showed that EPHA2 overexpression was related to increased tumor cell resistance to 5-FU and afatinib, a multi-kinase inhibitor." (PMID 39839790, 2024). "Despite various targeted strategies against EphA-2 and IL-13Rα2 to curb tumor growth, the efficacy of these interventions remains constrained." (PMID 38612592, 2024). "In glioma cells, EphA2 inhibition by siRNA approaches decreased tumor cell proliferation and induced apoptosis." (PMID 39596256, 2024). "constructed one such VV encoding a BiTE consisting of a scFv for CD3 and one specific for EphA2, a tumor cell surface antigen, named EphA2-TEA-VV." (PMID 38558795, 2024). "Briefly, we isolated EphA2-positive microvesicles (EphA2-MV) from the culture medium of EphA2+ tumor cells (143B and MG63), and loaded them with methotrexate (EphA2-MV/MTX)." (PMID 38433190, 2024). "BCY18469 showed high affinities, EphA2 specificity, and a favorable biodistribution profile with excellent tumor targeting properties at early timepoints and renal-mediated clearance." (PMID 39239524, 2024). "The authors found through an IHC study that the overexpression of the EphA2 protein was correlated with poor tumor differentiation and regional lymph node metastasis." (PMID 39839790, 2024). "Studies have revealed that EphA2 overexpression enhances the invasiveness of GSCs in vivo through Akt signalling, contributing to tumour stem properties." (PMID 38660136, 2024). "Extracellular stimuli from the tumor microenvironment plays an important role in modulating EphA2 oncogenic function." (PMID 39596256, 2024). "This variability in expression profiles, along with the capacity of IL-13Rα2 to influence tumor cell survival and proliferation via receptor signaling mechanisms, renders IL-13Rα2 and EphA-2 promising targets for cancer therapy." (PMID 38612592, 2024). "In summary, EphA2 plays a key role in CRC tumor growth and angiogenesis, resulting in poor prognosis and resistance to cetuximab therapy." (PMID 38651144, 2024). "The two most frequently occurring gene pairs were observed in three tumor types, EPHA2-ATM and EP300-ATM gene pairs." (PMID 39160568, 2024). "The ephrinA1 ligand and EphA2 are co-expressed in various types of human malignant tumor cells such as in breast cancer and Kaposi’s sarcoma, influencing tumor neovascularization." (PMID 39839790, 2024).
tumor (continued). "Among agonists, which are designed to recover tumor-suppressing ligand-dependent activity of EphA2, the small molecule doxazosin showed good preclinical results in in vitro and in vivo cancer models." (PMID 39596256, 2024). "In Eph/ephrin signaling, EphA2, EphB4 and EphrinB2 have been extensively studied especially in tumor." (PMID 38630320, 2024). "EphB receptors, particularly EphB2, are crucial for maintaining cellular homeostasis and regulating stem cell function, while EphA2 and ephrinA1 contribute to tumor progression and malignant transformation." (PMID 39839790, 2024). "Significant differences in serum EphA2 levels were observed in patients according to tumor size (p = 0.0346), depth of invasion (p = 0.0311), and lymphatic invasion status (p = 0.0431)." (PMID 39766211, 2024). "SPECT imaging with [111In]In-BCY18469 was also in line with the findings in the PET and biodistribution studies, and further confirmed the high accumulation of BCY18469 in EphA2-overexpressing tumor tissue as well as the rapid tumor uptake and clearance." (PMID 39239524, 2024). "The interleukin-13 receptor α2 (IL-13Rα2) and the erythropoietin-producing hepatocellular receptor A2 (EphA2) have been identified as playing crucial roles in tumor growth and progression." (PMID 38612592, 2024). "Based on the preclinical and translational evidence supporting a specific role of EphA2 in cancer, different approaches have been developed and tested in recent time to block its activity in tumor cells." (PMID 39596256, 2024). "The receptors EphA-2 and IL-13Rα2 are notably overexpressed on tumor cells in these subtypes compared to normal epithelial cells, suggesting their potential as targets for CAR T-cell therapy." (PMID 38612592, 2024). "In vivo both types of CAR-T cells inhibited tumor growth, but EphA2-a-CAR-T cells showed better activity against GBM." (PMID 38339374, 2024). "The difference in gene expression between the two types of EphA2-CAR-T cells was examined using ribonucleic acid (RNA) sequencing to find out why EphA2-a-CAR-T cells showed higher anti-tumor activity." (PMID 38339374, 2024). "Data from the literature demonstrate that the ubiquitin proteosome (UPS) machinery plays a significant role in modulating EphA2 protein stability, with relevant implications on EphA2 action in tumor cells." (PMID 39596256, 2024). "Recent studies have shown that EPHA2 is highly expressed in a variety of tumors and is closely related to the prognosis of tumor patients." (PMID 37057290, 2023). "The phosphorylation of EphA2 is widely involved in various life activities, especially in tumor cells." (PMID 37179400, 2023). "After it is primed, the CAR-T cells are locally induced to express a second chimeric receptor targeting two more homogeneous tumor-specific antigens [EPH receptor A2 (EphA2) antigen or IL13Rα2 antigen] so as to switch on their highly specific killing program." (PMID 37131214, 2023). "The levels of EphA2+ EVs correlated with staging and tumor progression, with a discriminatory sensitivity only modestly diminished for early stages of PDAC vs non-cancerous diseases (91%) or pancreatitis (86%) comparisons." (PMID 36614326, 2023). "Sorafenib inhibited HIFU ablation-induced progression of the residual tumor by suppressing HIF-2α/VEGF-A/EphA2 pathway in HCC." (PMID 36814489, 2023). "First, tumor growth was assessed after different treatments that suppressed TrkA kinase activity (entrectinib), EphA2 expression (by siRNA) or both." (PMID 38072918, 2023). "Ephrin receptor A2 (EphA2) plays dual functions in tumorigenesis through ligand-independent tumor promotion or ligand-dependent tumor suppression." (PMID 37816703, 2023). "We found EphA2- and Wee1-targeted therapies had synergistic effects in vitro, and the combination therapy led to enhanced anti-tumor efficacy in vivo." (PMID 36835335, 2023).